SRC (SRC proto-oncogene, non-receptor tyrosine kinase)
Diseases named in the same sentence as SRC in open-access papers (continued):
Sharing a sentence is not in itself a finding about the gene and the disease.
tumor (continued). "More specifically, in bladder cancer, two circRNAs have been reported to disturb FAK/SRC-mediated signaling and result in reduced tumor invasion and metastasis." (PMID 34205978, 2021). "MCL1 has also been shown to promote tumor invasiveness via interaction with Cofilin 1, a cytoskeletal remodeling protein, and phosphorylated SRC." (PMID 34469478, 2021). "In contrast, the two kinases that positively regulates SIAH2, namely p38 and SRC, both have well-established tumor promoting functions." (PMID 33842469, 2021). "Taken together, our results show that SRC is a transcriptional target of YAP in HCC cells and SRC inhibitors are able to suppress YAP-induced tumor cell migration." (PMID 34862372, 2021). "Taken together, our results suggest the combination usage of HTR1E specific agonist and SRC inhibitors to be an efficient way to inhibit the growth of OC primary tumor and its peritoneal dissemination." (PMID 34093864, 2021). "We selected src42A, which is a Drosophila homolog of human oncogene SRC, for further investigation given its capability of promoting tumor metastasis." (PMID 34862372, 2021). "Studies have indicated that EGFR receptors and c-SRC were co-overexpressed in 70% of breast tumors and were shown to work together to promote tumor growth in a mice xenograft study." (PMID 34193161, 2021). "Multiple studies support the role of SRC in inducing the transition of TGFβ signaling from tumor suppressive to oncogenic." (PMID 34193161, 2021). "The expression of the additional markers (AKT, SRC, mTOR, NF-κB, Ki-67) are clues for the aggressiveness of the tumor." (PMID 33313992, 2021). "We found that the expression of SRC in the baseline tumour tissues correlated with improved survival benefits, but predicts worse ICT response." (PMID 33830879, 2021). "In this study, we found that Yki directly induces the transcription of src42A, a homolog of human oncogene SRC, to promote cell migration, a key step of tumor metastasis." (PMID 34862372, 2021). "Taken together, our study identifies a conserved Yki/YAP-Src42A/SRC positive feedback loop promoting tumor cell migration and provides SRC as a potential therapeutic target for YAP-related malignancies." (PMID 34862372, 2021). "G3BP2 constitutes a member of the RAS GTPase-activating proteins and is involved in tumor invasion by promoting SRC and FAK phosphorylation." (PMID 34205978, 2021). "The expression of additional markers (AKT, SRC, mTOR, NF-κB, Ki-67) emphasized the aggressiveness of the tumor." (PMID 33313992, 2021). "And reactivation of serotonin/HTR1E to inhibit downstream SRC-mediated tumor promoting signaling pathways by the specific HTR1E agonist or the specific SRC inhibitor is a promising strategy to inhibit chronic stress-promoted OC growth and dissemination." (PMID 34093864, 2021). "In tumors, EGFR receptors have been shown to work synergistically in coordination with SRC and other tyrosine kinases, promoting tumor progression." (PMID 34193161, 2021). "The oncogenes Kristen rat sarcoma 2 viral oncogene homolog (KRAS), epidermal growth factor (EGF) and SRC are transferred by exosomes to recipient tumor cells to promote tumor invasion." (PMID 33396739, 2020). "PD/SRC are considered biologically distinct from other pathologic types, which themselves differ from tumor location and degree of differentiation." (PMID 32842507, 2020). "In particular, a study identified a gene expression signature mirroring the activation status of the SRC pathway, which can predict the sensitivity of a broad range of tumor cell lines to the SFK inhibitor SU6656." (PMID 32664483, 2020). "Upregulation of mTOR and fibroblast growth factor receptor 3 (FGFR3) inhibits tumour growth activated by tyrosine-protein kinase cellular sarcoma (c-SRC)." (PMID 33023154, 2020).
tumor (continued). "The antibody used in TR1801‐ADC is a nonagonistic binder that enhances the safety of our ADC by reducing downstream signaling of cMet (PI3K/AKT, ERK/MAPK and SRC/focal adhesion kinase pathways) and potential activation of tumor‐promoting events." (PMID 31736230, 2020). "SRC one of the SRC family kinases (SFKs) is involved in aggressive tumor proliferation, migration, and invasion in numerous malignancies." (PMID 33193697, 2020). "In order to assess if the identified kinases in the invasion assay correlate with expression levels in tumors from GC patients, mRNA and protein expression levels for FRK, DDR1, SIK2 and SRC were assessed in tumor samples from GC patients." (PMID 32082487, 2020). "The first issue for this defeat is connected to the incapacity of SRC-targeting drugs to reach the tumor site, because of the poor permeability of the BBB." (PMID 32545574, 2020). "Among such key kinases, a recent study showed that SRC in endosomal membranes promoted exosome secretion and tumor progression." (PMID 32204513, 2020). "The results of MTT assays showed that when YAP1 or SRC of hCAF was knocked down, its conditioned medium’s promotion effect on the proliferation capacity of two tumor cells was weakened." (PMID 32066485, 2020). "The interaction of hyaluronic acid and the CD44 receptor, leads to SRC activation, promoting tumor progression and radioresistance." (PMID 33020459, 2020). "Not only that, if YAP1 or SRC of hCAF was knocked down, then its conditioned medium cannot promote tumor cell invasion." (PMID 32066485, 2020). "SRC, ephrinB, EGFR, and HER2 signaling are inhibited by PTPN13 that limits anchorage-independent cell growth (SRC), cell proliferation (HER2 and EGFR), and also invasion and tumor aggressiveness (SRC, HER2)." (PMID 33322542, 2020). "Together these observations fit with the well-established oncogenic role of SRC and its downstream effectors favoring aggressive tumor phenotypes by promoting invasion and metastatic dissemination." (PMID 31731442, 2019). "The changes in tumor cell metabolism after EPHB4 inhibition were associated with MYC downregulation, likely mediated by the SRC/p38 MAPK/4EBP1 signaling cascade, known to impair cap-dependent translation." (PMID 31641103, 2019). "When the clinical relevance of active SRC was analyzed separately by tumor site in our cohort of HNSCC patients, striking differences were observed." (PMID 31731442, 2019). "Partial knockdown of both YAP and TAZ, through stable expression of tandem YAP and TAZ miR30-based shRNAs, significantly reduced this SRC-mediated tumor growth and extended mouse survival and also significantly reduced metastasis formation." (PMID 30559289, 2019). "In other tumor cell models, a 24-hour treatment with dasatinib efficiently inhibited SRC phosphorylation at Y418 while upregulating total SRC levels." (PMID 31382448, 2019). "Reciprocally, our results also show that YAP/TAZ activation is critically important downstream of the long-established oncogene, SRC, and link these separately discovered, powerful drivers of tumor progression." (PMID 30559289, 2019). "How SLAP counteracts SRC signalling in CRC tumours remains to be clarified, but several mechanisms can be envisaged." (PMID 31091767, 2019). "We herein provided unprecedented evidence for the differential clinical impact of SRC expression in HNSCC patients depending on the tumor site." (PMID 31731442, 2019). "The spontaneous pulmonary metastasis is proposed to be attributable to activation of SRC cascades in the primary PDX tumor." (PMID 31888763, 2019). "It has been demonstrated that aberrant SRC activity plays a central role in all stages of tumorigenesis from malignant transformation to tumor progression and ultimately development of metastatic disease." (PMID 31382448, 2019). "Recently we showed that CD90 (THY1) expression controls tumor cell migration/adhesion mainly through SRC signaling." (PMID 31064137, 2019).
tumor (continued). "Nevertheless, our results indicate that SRC-mediated YAP/TAZ activation drives tumor growth and metastasis and suggest that this pathway is a potential therapeutic target." (PMID 30559289, 2019). "Overall, SRC inhibitors have demonstrated potent anti-tumor activity in preclinical models, although they are largely ineffective for the treatment of late-stage solid tumors." (PMID 31731442, 2019). "Our results reveal clear differences in the prognostic relevance of SRC expression in HNSCC patients depending on the tumor site." (PMID 31731442, 2019). "We propose that this activity against regulators of SRC account for the ability of 1, 2, 2–3 and 3 to suppress invasion, a key first step in tumor metastasis." (PMID 31026276, 2019). "The expression of p-SRC (Tyr419) was also confirmed by Western blot analysis in a subset of tumor samples compared to patient-matched normal tissues and in a panel of HNSCC-derived cell lines." (PMID 31731442, 2019). "Matrix cross-linking through lysil oxydases (LOXs) increases matrix stiffness, integrin-dependent signaling, and SRC-dependent cell proliferation, resulting in facilitated tumor progression and metastasis." (PMID 31336983, 2019). "When examining separately each tumor site subgroup, we strikingly observed that the correlations between SRC expression and the SRC-related proteins FAK, ASAP1, and HERG1 were specific to the larynx and not the pharynx." (PMID 31731442, 2019). "The impairment of tumor cell metabolism arises due to MYC deactivation as a result of the SRC-p38 MAPK-4EBP1 signaling." (PMID 31641103, 2019). "Our results uncovered striking differences in the prognostic relevance of SRC expression in HNSCC patients depending on the tumor site." (PMID 31731442, 2019). "Compelling evidence indicates that in human CRC cells, SLAP acts as a tumour suppressor by controlling SRC oncogenic activity." (PMID 31091767, 2019). "ß1 integrins induce adhesion-dependent activation of the focal adhesion kinase (FAK) and proto-oncogene tyrosine-protein kinase SRC, leading to proliferation, migration, invasion and the survival of tumor cells bound to the ECM." (PMID 29783778, 2018). "The SRC expression level in HCC tissues was obviously up-regulated than in matched non-tumour tissues (P < 0.001)." (PMID 29780284, 2018). "SRC has been reported to be overexpressed and activated in late stage poor outlook EOC and in vivo xenograft data has shown that inhibition of SRC activity reduces tumour growth." (PMID 29435137, 2018). "We evaluated the expressions of HER2, c-SRC and ER in the mouse tumor samples using immunofluorescence staining." (PMID 29720121, 2018). "As upregulation of the proangiogenic signaling cascades has been shown to play a crucial role in angiogenesis, the global antiangiogenic effect of SRC inhibitor represents a promising approach for targeting tumor angiogenesis." (PMID 29739921, 2018). "Loss of function of merlin encoded by the NF2 tumor suppressor gene leads to activation of multiple mitogenic signaling cascades, including platelet-derived growth factor receptor (PDGFR) and SRC in Schwann cells." (PMID 28427224, 2017). "HA binding promotes the activating phosphorylation of c-SRC at tyrosine 419 (Y419) in certain epithelial tumor cells." (PMID 28107185, 2017). "Both HRAS and SRC are known for their oncogenic activity, thus the inhibitory activity of HRAS toward SRC suggests tumor suppressive activity." (PMID 28815022, 2017). "To show SRC signaling is activated, we found phosphorylation of paxillin is upregulated suggesting tumor progression." (PMID 28396832, 2017). "In summary, for the first time, our study provides valuable insight into the anti-tumour mechanism of rGal3C involving integrin/FAK/SRC pathway and NDRG1 in HCC on a proteomics level." (PMID 28701735, 2017). "Our results suggested the possible anti-tumour mechanism of rGal3C in HCC involved in Integrin/FAK/SRC pathway and NDRG1." (PMID 28701735, 2017).
tumor (continued). "Immunoblotting and immunofluorescence results revealed that the possible anti-tumour mechanism of rGal3C in HCC involved the FAK/SRC pathway." (PMID 28701735, 2017). "Mutations in PIK3CA (25.9%), INPP5B (30.8%), SRC (99%) and TSC2 (46.7%) were observed in Tumor #3, and Tumor #4 harbored an NF1 gene mutation (43.5%)." (PMID 27057633, 2016). "Phosphorylated ERK and SRC are frequently elevated in resistant tumours suggesting that paradoxical activation of the MAPK pathway and growth factor signalling are involved in resistance development." (PMID 27835901, 2016). "Taken together, we showed that, the tumor microenvironment activated an integrin β3/FAK/SRC/EGFRvIII signaling axis, where integrin β3 was the most important regulator on modulating EGFRvIII activity and GBM cell invasion in vitro." (PMID 26717039, 2016). "Consistently, SLAP inactivation in CRC dramatically increases EPHA2 protein level and amplifies the SRC/EPHA2/AKT signaling cascade that promotes tissue invasion of tumor cells." (PMID 26788993, 2016). "This would render tumor cells less dependent on SRC oncogenic signaling and, consequently, rather resistant to a SRC-based therapy." (PMID 26788993, 2016). "Here, we showed significance of functional interactions between EGFRvIII and integrin β3 via receptor cross-linking and mutual stimulation in formation of an integrin β3/FAK/SRC/EGFRvIII signaling axis, and in rapid tumor progression." (PMID 26717039, 2016). "Studies have indicated that EGFR mutations and possibly other abnormalities of EGFR leading to enhanced SRC expression are important determinants of tumor sensitivity to SRC kinase inhibitors." (PMID 27438149, 2016). "It is well-established that SRC is necessary for tumor progression in many tumor types, including NSCLC." (PMID 27756880, 2016). "In the cell lines considered in this study, SRC was constitutively active which has also been observed in patient tumor samples." (PMID 26517812, 2015). "Here, we report that reduced SRC and LYN methylation was associated with advanced stage GC, deeper tumor invasion and with lymph node or distant metastasis." (PMID 26460485, 2015). "Activated SRC induces integrin αvβ5-dependent tumor cell adhesion to fibroblasts and tumor cell motility." (PMID 25973543, 2015). "Increased protein and mRNA expression of SRC and LYN and reduced CKB expression were associated with advanced stage, deeper tumor invasion, and the presence of lymph node and distant metastases (p < 0.05, for all comparisons)." (PMID 26460485, 2015). "Reduced percentage of SRC, LYN and CKB methylation were associated with advanced stage, deeper tumor invasion, and the presence of lymph node and distant metastases (p < 0.05, for all comparisons)." (PMID 26460485, 2015). "Dasatinib-mediated inhibition of SRC slowed tumour progression and metastasis of human PDAC cells in an orthotopic mouse model, and stimulated migration, invasion, and apoptosis in human and murine PDAC cells." (PMID 26588899, 2015). "As for SRC and LYN, MYC immunoreactivity or elevated mRNA expression was previously associated with late onset, advanced stage, deeper tumor extension and the presence of metastasis." (PMID 26460485, 2015). "A gradual significant increase in SRC protein (by western blotting) and mRNA expression was observed corresponding to the tumor stage (p < 0.008, for most of the comparisons; Mann-Whitney test followed by Bonferroni correction)." (PMID 26460485, 2015). "The results suggest that targeting SRC is a major mechanism by which miR-203 exerts its tumor-suppressive function." (PMID 25140799, 2014). "As the downstream signal transduction pathway of SRC, activation of Ras/ERK pathway is associated with cell transformation and tumor progression." (PMID 25140799, 2014). "AKT is a downstream protein of SRC and is dramatically associated with EMT, invasion and metastasis in tumor progression." (PMID 25398131, 2014).
tumor (continued). "The results reveal a critical role for miR-203 as a tumor suppressor in lung carcinogenesis through the repression of SRC translation." (PMID 25140799, 2014). "SRC and CRK-associated substrate phosphorylation is an important promoter of PDAC anchorage-independence and tumor progression." (PMID 22384141, 2012). "In our study, endogenous wild-type SRC was activated by an upstream RTK, more closely reflecting the effects of activation of endogenous SRC in tumor cells." (PMID 21049007, 2010). "The Y561-dependent substrates revealed a set of putative SRC substrates and subsequent bioinformatics analyses of these targets in human tumor datasets identified potential biomarkers of SRC activation in human tumors." (PMID 21049007, 2010). "To address the relevance of the identified SRC substrates to tumorigenesis, we conducted comparative bioinformatics analysis on phosphoproteomic datasets generated from human tumor samples." (PMID 21049007, 2010). "Studies also suggest that SRC may mediate ROS-induced signaling cascades, amplifying inflammation and tumor aggressiveness in the biliary tract." (PMID 41300430, 2025). "Additionally, we analyzed the DDR2, SHP2 and SRC activity levels in the tumor lysates using Western blotting, observing a significant decrease in protein levels for the dual inhibitor group relative to the untreated group." (PMID 39941857, 2025). "mRNA levels of SRC were significantly higher in PCa tissues compared to adjacent non-tumor tissues." (PMID 40872629, 2025). "A positive correlation between the expression of SRC and PD-L1 was observed in tumor tissues." (PMID 40599804, 2025). "SRC expression in HER2-positive tumor cells has been found to be consistent with HER2 expression, and evidence suggests that SRC may act as a link between EGFR and MET." (PMID 40181988, 2025). "Our docking prediction raises the hypothesis that dasatinib’s efficacy might be augmented in CD2AP-high tumours by concurrently inhibiting SRC kinases and disrupting CD2AP-dependent invasive structures." (PMID 41425578, 2025). "Finally, we validated that co-inhibition of AXL and SRC significantly reduced tumor growth in A549 xenografts." (PMID 39941857, 2025). "The localization of AKT1 and ESR1 in tumor cells, alongside SRC and IL6 in myeloid cells, highlights potential mechanisms through which the decoction impacts tumor-immune interactions, potentially altering immune surveillance and tumor progression in high-risk locally advanced NPC." (PMID 40746726, 2025). "Previous studies have shown that secreted ANGPTL4 interacts with integrin β1 and β5 on the cell surface, triggering downstream signaling pathways such as focal adhesion kinase (FAK) and proto-oncogene tyrosine-protein kinase SRC, thereby affecting tumor progression." (PMID 39910592, 2025). "We infused NK-92 cells overexpressing NEDD4L and its three substrates into tumor-bearing Hu-SRC mice to evaluate whether NEDD4L-inhibited ferroptosis improved NK cell antitumor immunity." (PMID 40399270, 2025). "Surprisingly, compound 9c heightened the activation of ERK, probably due to the activation of alternative pathways in tumor cells resulting from the potent inhibition of EGFRs, as it has reported that the EGFR inhibitor causes the activation of ERK signaling mediated by SRC bypass." (PMID 40076615, 2025). "Furthermore, NFKBIA upregulation suppresses NF-κB survival signaling and activates SRC-FHIT tumor-suppressive pathways, and CCL15 downregulation diminishes chemotactic and angiogenic activity." (PMID 41465234, 2025). "As previously discussed, the constitutive activation of signaling pathways like JAK-STAT and SRC/TNK2 in CSF3R-altered neoplasms presents opportunities for targeted interventions with documented efficacy using JAK inhibitors such as ruxolitinib in these neoplasms." (PMID 40806796, 2025).